STAT3 (signal transducer and activator of transcription 3)
Diseases named in the same sentence as STAT3 in open-access papers (continued):
Sharing a sentence is not in itself a finding about the gene and the disease.
cancer (continued). "Many studies have shown that blocking the activation of STAT3 will reduce the survival rate, proliferation, migration, and invasion of cancer cells." (PMID 29226125, 2017). "Our study shows that HBV regulates the STAT3 signaling pathway via miR-340-5p to facilitate cancer cell migration." (PMID 28413603, 2017). "Targeting STAT3 in cancer treatment has shown therapeutic benefits in both preclinical and clinical studies." (PMID 28594363, 2017). "IL-17A is a cytokine produced by immune cells to promote tumor growth via up-regulation of IL-6, IL-8, G-CSF, VEGF, MMP-2, MMP-9, and p-STAT3 expression in cancer cells and tissues." (PMID 29212184, 2017). "ATF4 also promotes multidrug resistance (MDR) expression, a major challenge to cancer treatment, through transactivation of signal transducer and activator of transcription 3 (Stat3)." (PMID 28860159, 2017). "Signal transducer and activator of transcription 3 (STAT3) signalling is a major pathway in cancer initiation and malignant progression." (PMID 28445971, 2017). "Whereas it was unclear how cdc25a expression is activated in these early embryos, our studies point to Stat3 as a regulator of cdc25a during zebrafish development, paralleling this role in cancer." (PMID 28222105, 2017). "The nuclear localization of the STAT3‐NF‐κB‐IκBα complex was recently shown to be regulated by Rac‐1 in starved cancer cells." (PMID 28264935, 2017). "Specifically, EGCG differently regulates the levels of STAT1, STAT3 and Bcl-xL proteins in normal cochlear and cancer cells." (PMID 28703809, 2017). "STAT3-DNMT1 interaction implicates new functional roles of STAT3 in epigenetic gene silencing in human cancer." (PMID 29137356, 2017). "Further, JAK2/STAT3 signaling pathway is involved in the sustaining of self-renewal and tumorigenicity, which is constitutively phosphorylated in cancer cells." (PMID 29348843, 2017). "STAT3, which regulates the expression of genes involved in cancer progression, is an attractive target for inhibition in SCLC since it is found in primary SCLC tissues and in SCLC cell lines." (PMID 29299146, 2017). "Although prior research has shown that STAT3 can be targeted in various cancers using small molecular inhibitors and natural compounds, there is no clinically available STAT3 inhibitor." (PMID 28114390, 2017). "Studies have demonstrated that niclosamide is a potential anticancer drug against cancers with activated STAT3 given that it can disrupt STAT3 transcription." (PMID 28877265, 2017). "STAT3 staining was mainly distributed in the cytoplasm and nucleus in cancer cells, and nuclear localization was increased in advanced-stage CRC." (PMID 29242509, 2017). "The implications of STAT3 in various cancers and in cancer initiation, development, metastasis, and drug resistance make it a desirable target for therapeutic target." (PMID 29179470, 2017). "Taken together, our results suggest that targeting acetyl-STAT3 (K685) provides potential therapeutic opportunity to treat a subset of human cancers." (PMID 29137356, 2017). "In cancer tissues, apigenin reduced phosphorylation of both NF-κB at p65 and STAT3 in a dose-dependent manner." (PMID 29245972, 2017). "Here we demonstrate that centrosome clustering is a Stat3-dependent function, revealing a new mechanism to target cancer cells by Stat3 inhibitors." (PMID 28474672, 2017). "Previous studies have revealed that STAT3 is persistently activated in a wide range of human malignancies, and it exerts diverse roles in cancer cell proliferation, epithelial to mesenchymal transition (EMT), invasion and metastasis." (PMID 28738823, 2017). "Macrophages contribute cancer-initiating inflammatory responses because expression of the anti-inflammatory transcription factor STAT3 is inhibited." (PMID 28467800, 2017). "For example, both tanshinone I and acacetin are natural materials that inhibit STAT3 activation by preventing STAT3 705 Tyr-phosphorylation in ECs and cancer cells." (PMID 28978186, 2017).
cancer (continued). "STAT3 is known to be abnormally activated in autoimmune diseases, chronic inflammation and in a large percentage of human cancers." (PMID 29162862, 2017). "Previous studies have revealed that CISCFE can induce apoptosis and inhibit cell proliferation through signal transducers and activators of transcription factors-3 (STAT-3) and NF-κB signaling pathways in different cancer cell lines." (PMID 28245556, 2017). "For example, STAT3 activation in several types of cancer cells was significantly induced by the direct coculture of macrophages and cancer cells." (PMID 29207614, 2017). "It has been established that signal transducer and activator of transcription 3 serves as an oncoprotein in various human cancers; targeting it is therefore a reasonable approach for emerging cancer therapies." (PMID 28654902, 2017). "It has been previously reported that silibinin suppresses the activation of STAT3 leading to the inhibition of cell growth and induction of apoptosis in a number of cancer cell lines in vitro." (PMID 28027688, 2017). "TM4SF4-triggered OPN expression forms the core for the persistent reinforcement of EMT or cancer stemness by creating a positive feedback autocrine loop with JAK2/STAT3 or FAK/STAT3 pathways." (PMID 29254164, 2017). "Signal transducer and activator of transcription 3 (STAT3) is an oncogenic transcription factor that is constitutively activated in many human cancers." (PMID 28534824, 2017). "Leptin is known to activate a number of different signaling pathways, particularly the JAK2/STAT3 pathway, including in cancer cells." (PMID 29212170, 2017). "The data presented in this report, for the first time, revealed a defect in the c‐kit/SCF axis, as wells as in the c‐myc, and STAT3 expression in NK cells in patients with cancer." (PMID 28695716, 2017). "We can suggest a direct relationship between the alterations of c‐kit, c‐myc, and STAT3 expression in NK cells in patients with cancer." (PMID 28695716, 2017). "We then focused on PI3K/Akt and STAT3 signaling pathways, both of which have been extensively studied to promote cancer cell proliferation and invasion, to confirm the activation of the two pathways by ING5 knockdown." (PMID 28903339, 2017). "These evidence demonstrated that JAK/STAT3 signaling pathway plays crucial roles in the tumorigenesis and progression of cancer." (PMID 28750679, 2017). "Considering STAT3 was an important node that mediated cellular responses to cytokines and acted as crucial regulator of PD-L1 and CD86 in cancers, we focused our attention on STAT3." (PMID 29152078, 2017). "The potential space of shikonin in developing novel anti-cancer agents encouraged us to carry out the investigation of the probable binding mode with STAT3." (PMID 28588262, 2017). "Notwithstanding, the prognostic role of p-STAT3 on cancer patient outcome seems to be conflicting among various solid cancers." (PMID 28594363, 2017). "Excessive production of ROS especially targets various signaling pathways triggering the death of cancer cells, such as signal transducer and activator of transcription 3 (STAT3) signaling cascade." (PMID 28054986, 2017). "We also found that the STAT3 acetylation was decreased when exogenous Hdac7 was expressed in human cancer cells, H1299 and A549." (PMID 29126425, 2017). "We believe that combination therapies with CNL and STAT3 inhibitors should be explored in STAT3-dependent cancers." (PMID 29263930, 2017). "Other prior research has demonstrated that STAT3 interacts with the Skp2 pathway to activate the motility and invasion of cancer cells." (PMID 28157698, 2017). "Constitutive STAT3 activation was reported with various human cancers, usually with poor outcome, as a promising target for cancer therapy." (PMID 28422733, 2017). "Some constituents occurring in AR, e.g., gallic acid, catechin, and epicatechin, have been reported to exert anti-cancer effects by inhibiting STAT3 signaling." (PMID 28503147, 2017).
cancer (continued). "TFF3-mediated activation of STAT3 has also been previously reported to stimulate progression of different cancers." (PMID 29100386, 2017). "STAT3 activation has been shown to induce drug resistance in various cancers through multiple mechanisms." (PMID 28740138, 2017). "In summary, our data reveal an abnormal expression of c‐myc, с‐kit, and STAT3 expression in NK cells from the peripheral blood of patients with different types of cancer." (PMID 28695716, 2017). "Our data suggest that targeting acetylation of STAT3 (K685) by small molecule inhibitors is a plausible new approach to treat human cancers." (PMID 29137356, 2017). "The levels of STAT3 have also been found to be elevated in many cancers where they stimulate cell proliferation (via cyclin D1) and induction of anti-apoptotic proteins (such as Bcl2)." (PMID 28467474, 2017). "It has previously been shown that B7-H3 regulates the expression of Bcl-2, Bcl-xL, and Bax via the JAK2/STAT3 signaling pathway to increase the anti-apoptotic ability of cancer cells." (PMID 29088829, 2017). "We found that cryptotanshinone substantially suppressed cancer cell growth while it promoted cell apoptosis by inhibiting the phosphorylation of STAT3 at Tyr705 and its blocking nuclear translocation." (PMID 28654902, 2017). "STAT3 has been widely recognized as an oncogene in various cancers and has been confirmed to be constitutively active in TNBC." (PMID 28030809, 2017). "The elevated leptin-led promotion of cancer progression is associated with the Janus kinase 2 (JAK)-signaling transducer and activator of transcription (STAT)-3 signaling pathway and STAT3 target gene expression." (PMID 28750624, 2017). "As STAT3 is identified as an oncogene aberrantly activated and expressed in malignant transformation and tumorigenesis, our study thus holds promise for cancer diagnosis and therapy." (PMID 28661466, 2017). "CuB was previously reported to block STAT3 signaling by inhibiting its phosphorylation in various cancer cell lines." (PMID 27418139, 2017). "One important mechanism is interfering with the activation of IL-6/Jak-2/STAT3 signalling pathway which was found to have a pivotal role in cancer development and progression." (PMID 28970500, 2017). "Collectively, our findings indicate that TM4SF4-triggered OPN expression is involved in the persistent reinforcement of EMT or cancer stemness by creating a positive feedback autocrine loop with JAK2/STAT3 or FAK/STAT3 pathways." (PMID 29254164, 2017). "STAT3 is activated and translocated into nucleus to bind DNA, leading to target oncogenes transcription which participate in cancer initiating, survival, proliferation, angiogenesis, and resistance to apoptosis induced by conventional therapy." (PMID 28672024, 2017). "According to the results of our immunofluorescence double staining experiments in cancer cell lines treated with IL-6 or AG490, we found that p-STAT3 activation is more closely linked with vimentin expression than VE-cadherin expression." (PMID 29333928, 2017). "STAT3 signaling is regarded as a target for cancer treatment due to its important function in a variety of malignant tumors." (PMID 28415635, 2017). "As a transcription factor and activator, STAT3 links to metastatic progression of multiple different cancer types, including lung, skin, liver, ovarian, kidney and colon cancer." (PMID 28470949, 2017). "Intracellular ROS are important to maintain cancer cell survival through the activation of oncogenic pathways such as STAT3 that is strongly involved in PEL cell survival." (PMID 29179721, 2017). "A key regulator of G1-S and G2-M transitions, CDC25a is overexpressed in human cancers driving abnormal cell proliferation downstream of multiple signaling pathways including STAT3." (PMID 28222105, 2017). "We demonstrate that Stat3 is also involved in the regulation of supernumerary centrosome clustering, revealing a new function for a critical cancer-related gene." (PMID 28474672, 2017).
cancer (continued). "STAT3 and HIF-1α, two major transcription factors that regulate VEGF, have been found to be consistently upregulated in various cancers including HCC and associated with poor clinical outcomes in patients." (PMID 28978924, 2017). "STAT3 has been reported as a proto-oncogene in several human cancers, suggesting significant potential for targeted therapy." (PMID 29023443, 2017). "Among many cancer-related processes, STAT3 has been shown to regulate cell migration and, hence, enhance the metastatic capability of prostate epithelium cancer cells." (PMID 28636670, 2017). "Upregulation of IL-6 and activation of STAT3 autocrine pathway have been shown to account for the major mechanisms of cancer cell resistance to therapy." (PMID 28077171, 2017). "As the downstream of IL-6/GP130, phosphorylation of STAT3, as well as STAT3 downstream target genes, were inhibited by Raloxifene in Hep-G2, Huh-7 and 7721 cancer cell-lines." (PMID 28430601, 2017). "Taken together, these data support the idea that gankyrin deletion leads to a reduction of pro-inflammatory cytokine responses and expression of cancer stem cell markers through inhibition of STAT3 and/or ERK activation." (PMID 28160571, 2017). "We further demonstrated that autocrine hGH promotion of cancer progression in HCC cells was mediated by STAT3 dependent inhibition of CLAUDIN-1 expression." (PMID 28617312, 2017). "Given that IL-6 can activate downstream STAT3, a key oncogene constitutively activated in many cancer including HCCs and contributing to cancer cell proliferation and survival, we examined hepatic STAT3 activation in both genotypes 10-month post DEN injection." (PMID 28036277, 2017). "STAT3, a transcription factor that is constitutively activated in several cancer types, is considered to be an oncogene." (PMID 29254202, 2017). "Niclosamide is able to inhibit signaling pathways such as Wnt/β-catenin, NF-κB (a regulator of inflammation), STAT3, and mTORC1 (a negative regulator of autophagy), depending on cancer cell type." (PMID 28877265, 2017). "We and others have reported that interruption of STAT3 impedes cancer cell growth and enhances apoptosis in HNSCC." (PMID 28877725, 2017). "MUC2 participates in STAT3-induced cell migration and E-cadherin downregulation in HT-29 cancer cells." (PMID 28725043, 2017). "A molecular cross‐talk between STAT3 and NF‐кB signal pathways has been reported 43 that promotes development and progression of cancer 44 and this possibly extends to AP‐1 also." (PMID 28155253, 2017). "MET activation triggers Ras-dependent ERK1/ERK2 activation and STAT3 signaling, which contribute to enhanced proliferation, survival and migration of cancer cells." (PMID 28420162, 2017). "STAT3 links inflammatory pathways to cancer development via miR-21, miR-155, miR-16 upregulation and NK-κΒ49,50." (PMID 29284790, 2017). "Cancer cells expressing constitutively activated STAT3 are more resistant to apoptosis and chemotherapy." (PMID 28864784, 2017). "STAT3 was found to be constitutively activated by aberrant upstream tyrosine kinase activity in a broad spectrum of cancer cell lines and human tumors, and it is considered a promising target for cancer therapy." (PMID 28738705, 2017). "Although STAT1 has been regarded as a tumor suppressor protein with some functions that oppose the tumorigenic role of STAT3, it can substitute for STAT3 in certain cancer cell lines and adopt a pro-tumorigenic role." (PMID 28636670, 2017). "STAT3, which can be triggered by cytokines and growth factors, was constitutively activated in some types of cancer." (PMID 28536310, 2017).
cancer (continued). "Several reports showed that the inhibition of STAT3 suppressed the growth of cancer cells and enhanced the sensitivity to anticancer agents in multiple types of cancer." (PMID 28399187, 2017). "A key central player of these signaling pathways is the protein Signal Transducer and Activator of Transcription 3 (STAT3) which was found constitutively activated in many cancer types including PCa." (PMID 28489571, 2017). "IL‐6 secreted by cancer cells activates STAT3, and induces downstream events, including cancer cell proliferation and apoptosis inhibition." (PMID 28618162, 2017). "It has also been shown to be an activator of a key oncogene, STAT3, known to mediate uncontrolled cell growth in many types of human cancers." (PMID 29371911, 2017). "CuB was previously reported to inhibit activation of STAT3 in cancer cells, so we evaluated the inhibitory effect of CuB on STAT3 in MM cells." (PMID 27418139, 2017). "STAT3 is an attractive cancer drug target molecule because of its over-expression and constituted activation in numerous cancers." (PMID 27861147, 2017). "In conclusion, this work is the first body of evidence demonstrating that CNL suppresses STAT3 phosphorylation in cancer cells and that STAT3 is a mediator of CNL-induced cell death." (PMID 29263930, 2017). "Accumulating studies reported that STAT3 signaling pathway played important roles in the stemness maintenance of cancer stem cell." (PMID 28750679, 2017). "All the compounds were tested against STAT3, A2780 and A2780cisR cancer cell lines, E. coli JW2496, and NF-κB." (PMID 28874704, 2017). "Previous studies have shown that some compounds occurring in AR exert anti-cancer effects by inhibiting STAT3 signaling." (PMID 28503147, 2017). "Signal transducer and activator of transcription 3 (STAT3) is constitutively activated in many types of cancers serves as a poor prognostic indicator and oncopromoter." (PMID 28036277, 2017). "This explains the phenomenon observed in our previous study, which showed that cancer-derived IL-6-induced T cell suppression in primary MDSCs by activating STAT3-dependent, nuclear factor-κB-mediated long-term IDO overexpression." (PMID 29326716, 2017). "Then we can draw that TAMs in malignant tumors tend to M2 subtype possibly through CXCL12/CXCR4/JAK2/STAT3 signaling pathway." (PMID 28630636, 2017). "DUSP22 was shown to be a negative regulator for STAT3 in cancer cells, but its role in antiviral responses is undetermined." (PMID 28886690, 2017). "Here, we determined the c‐myc, с‐kit, membrane‐bound SCF (mbSCF) and soluble SCF (sSCF) and STAT3 expression in NK cells in patients with different types of cancer." (PMID 28695716, 2017). "Constitutive activation of STAT3 has been observed in many cancers which results in the generation of immature myeloid and dendritic cells." (PMID 28659794, 2017). "Several lines of evidence have demonstrated that key molecules that are involved in cancer-related inflammation include NF-kB, STAT3, and major inflammatory cytokines, such as IL-1b, IL-6, IL-23, and TNF-a." (PMID 29232409, 2017). "STAT3 is frequently activated in a variety of cancers and plays important roles in multiple aspects of cancer aggressiveness." (PMID 28883791, 2017). "Many regulatory molecules involved in EMT and CSCs, including Snail, Dlx-2, HIF-1, STAT3, TGF-β, Wnt, and Akt, are implicated in the metabolic reprogramming of cancer cells." (PMID 28137309, 2017). "Conversely, stimulation with IL6 potentiated the migration of cells with RIP4 knockdown suggesting that sustained STAT3 signaling promotes the metastatic potential of these cancer cells." (PMID 28574510, 2017). "This investigation identifies a previously unrecognized mechanism, in which H3K23ac/TRIM24 functions as a mediator of EGFR/EGFRvIII activation of STAT3 signaling, thereby promoting tumorigenesis in human cancers." (PMID 29129908, 2017).